HLA-E (major histocompatibility complex, class I, E)
Description:
Non-classical major histocompatibility class Ib molecule involved in immune self-nonself discrimination. In complex with B2M/beta-2-microglobulin binds nonamer self-peptides derived from the signal sequence of classical MHC class Ia molecules (VL9 peptides - VMAPRT[V/L][L/V/I/F]L). Peptide-bound HLA-E-B2M heterotrimeric complex primarily functions as a ligand for natural killer (NK) cell inhibitory receptor KLRD1-KLRC1, enabling NK cells to monitor the expression of other MHC class I molecules in healthy cells and to tolerate self. Upon cellular stress, preferentially binds signal sequence-derived peptides from stress-induced chaperones and is no longer recognized by NK cell inhibitory receptor KLRD1-KLRC1, resulting in impaired protection from NK cells. Binds signal sequence-derived peptides from non-classical MHC class Ib HLA-G molecules and acts as a ligand for NK cell activating receptor KLRD1-KLRC2, likely playing a role in the generation and effector functions of adaptive NK cells and in maternal-fetal tolerance during pregnancy. Besides self-peptides, can also bind and present pathogen-derived peptides conformationally similar to VL9 peptides to alpha-beta T cell receptor (TCR) on unconventional CD8-positive cytotoxic T cells, ultimately triggering antimicrobial immune response. Presents HIV gag peptides (immunodominant KAFSPEVIPMF and subdominant KALGPAATL epitopes) predominantly to CD8-positive T cell clones expressing a TRAV17-containing TCR, triggering HLA-E-restricted T cell responses. Presents mycobacterial peptides to HLA-E-restricted CD8-positive T cells eliciting both cytotoxic and immunoregulatory functions. (Microbial infection) Viruses like human cytomegalovirus have evolved an escape mechanism whereby virus-induced down-regulation of host MHC class I molecules is coupled to the binding of viral peptides to HLA-E, restoring HLA-E expression and inducing HLA-E-dependent NK cell immune tolerance to infected cells. (Microbial infection) May bind HIV-1 gag/Capsid protein p24-derived peptide (AISPRTLNA) on infected cells and may inhibit NK cell cytotoxicity, a mechanism that allows HIV-1 to escape immune recognition. (Microbial infection) Upon SARS-CoV-2 infection, may contribute to functional exhaustion of cytotoxic NK cells and CD8-positive T cells. Binds SARS-CoV-2 S/Spike protein S1-derived peptide (LQPRTFLL) expressed on the surface of lung epithelial cells, inducing NK cell exhaustion and dampening of antiviral immune surveillance.
Synonyms: HLA-6.2; QA1
Tractability: Small molecule: it has a high-quality binding pocket. Antibody: UniProt places it where antibodies can reach, with high confidence; its Gene Ontology location is reachable by antibodies, with high confidence; UniProt predicts a signal peptide or a membrane-spanning region; the Human Protein Atlas places it where antibodies can reach. PROTAC: ubiquitination databases record sites on it.
Gene: Protein-coding gene on chromosome 6 (30,489,503 to 30,494,205, forward strand). Ensembl gene ENSG00000204592.
Subcellular location: Cell membrane; Golgi apparatus membrane; Secreted (Soluble HLA class I histocompatibility antigen, alpha chain E)
Subcellular location (Human Protein Atlas): Plasma membrane; Vesicles; Predicted to be secreted
Pathways (Reactome):
Immune System: Antigen Presentation: Folding, assembly and peptide loading of class I MHC; DAP12 interactions; DAP12 signaling; ER-Phagosome pathway; Endosomal/Vacuolar pathway; Immunoregulatory interactions between a Lymphoid and a non-Lymphoid cell; Interferon alpha/beta signaling; Interferon gamma signaling
Disease: SARS-CoV-2 activates/modulates innate and adaptive immune responses
Gene Ontology:
Molecular function: beta-2-microglobulin binding; MHC class I protein binding; natural killer cell lectin-like receptor binding; peptide antigen binding; protein binding; receptor ligand activity; signaling receptor binding; T cell receptor binding
Biological process: adaptive immune response; antibacterial humoral response; antigen processing and presentation of endogenous peptide antigen via MHC class Ib; antigen processing and presentation of exogenous peptide antigen via MHC class Ib; CD8-positive, alpha-beta T cell activation; defense response to Gram-positive bacterium; natural killer cell tolerance induction; negative regulation of natural killer cell activation; negative regulation of natural killer cell mediated cytotoxicity; negative regulation of T cell proliferation; positive regulation of antibody-dependent cellular cytotoxicity; positive regulation of CD8-positive, alpha-beta T cell activation; positive regulation of CD8-positive, alpha-beta T cell proliferation; positive regulation of immunoglobulin production; positive regulation of interleukin-13 production; positive regulation of interleukin-4 production; positive regulation of natural killer cell activation; positive regulation of natural killer cell cytokine production; positive regulation of natural killer cell mediated cytotoxicity; positive regulation of natural killer cell mediated immunity; positive regulation of natural killer cell proliferation; positive regulation of T cell mediated cytotoxicity; positive regulation of TRAIL production; positive regulation of tumor necrosis factor production; protection from natural killer cell mediated cytotoxicity; and 5 more
Cellular component: cell surface; extracellular exosome; extracellular region; Golgi membrane; MHC class I protein complex; MHC class Ib protein complex; plasma membrane; early endosome membrane; ER to Golgi transport vesicle membrane; external side of plasma membrane; lumenal side of endoplasmic reticulum membrane; phagocytic vesicle membrane; recycling endosome membrane
Genetic constraint (gnomAD): Loss-of-function variants: 25 observed, 45.96 expected, observed/expected ratio (o/e) 0.54, 90% interval 0.4 to 0.76. The upper end of that interval is the gene's LOEUF score, 0.76, which puts it in group 3 of 6, group 1 being the genes least tolerant of losing a copy. Missense variants: 343 observed, 485.92 expected, observed/expected ratio (o/e) 0.71, 90% interval 0.64 to 0.77. Synonymous variants: 161 observed, 199.65 expected, observed/expected ratio (o/e) 0.81, 90% interval 0.71 to 0.92.
Homologues: Orthologues: chimpanzee PATR-E (92% identical), macaque MAMU-E (86% identical), zebrafish si:ch211-147g22.4 (17% identical), zebrafish mhc1lia (15% identical). Paralogues in human: HLA-A (78% identical), HLA-B (77% identical), HLA-C (75% identical), HLA-G (72% identical), HLA-F (70% identical), MR1 (35% identical), HFE (34% identical), MICB (28% identical), FCGRT (27% identical), AZGP1 (27% identical), MICA (26% identical), CD1A (23% identical), and 10 more.
Diseases named in the same sentence as HLA-E in open-access papers:
HLA-E is named in the same sentence as 178 diseases in open-access papers, as found by Europe PMC text mining. Sharing a sentence is not in itself a finding about the gene and the disease. The quoted sentences say what the papers report.
viral infections (42 papers, 2010 to 2026). "Basal HLA-E expression can increase upon cellular stress caused by viral infection or heat shock and in inflammatory and cancer cells." (PMID 29709038, 2018). "The HLA-E alleles’ association with different viral infections seems to be discrepant." (PMID 33807915, 2021). "The upregulation in the expression levels of HLA-E, HLA-F and HLA-G in insulin-containing islets of patients with type 1 diabetes could conceivably be linked to a viral infection where the virus is attempting to shield itself from the immune system." (PMID 31820163, 2019). "Thus, the HLA-E alleles’ association with different viral infections seems to be discrepant." (PMID 31690066, 2019). "Instead, most reported HLA-E-restricted T cell responses in viral infection appear to adopt cytotoxic or effector functions." (PMID 41283666, 2025). "These insights highlight the therapeutic potential of designing HLA-E-restricted peptides that selectively modulate NK cell responses against viral infections." (PMID 40680069, 2025). "The reduction in MHC class I expression during viral infections further diminishes HLA-E levels, as MHC class I molecules provide the peptides necessary for optimal HLA-E expression and its interaction with NKG2A." (PMID 40391199, 2025). "Under normal circumstances, however, the low expression of HLA‐E and the binding dominance of the MHC class I signal peptide means that HLA‐E‐restricted T‐cell responses, directed at other HLA‐E‐binding peptides, are rarely primed in virus infections." (PMID 39753525, 2025). "The HLA-E/NKG2A axis was recently identified as one important immune evasive mechanism in other viral infections such as HCMV, Epstein–Barr virus (EBV), human immunodeficiency viruses (HIV), herpes simplex virus 1 (HSV-1), or human papillomavirus (HPV)." (PMID 39295866, 2024). "Although historically underappreciated in curative approaches for chronic viral infections, these data demonstrate that HLA-E-restricted NK cell responses impact SIV control in vivo, as has been found in mouse models for other viral infections." (PMID 34001890, 2021). "Over the past two decades, there has been a great interest in the study of HLA-E-restricted αβ T cells during bacterial and viral infections, including recently SARS-CoV-2 infection." (PMID 34446788, 2021). "There is increased appreciation that peptides presented via HLA-E during conditions of stress and viral infections influence the activation of NK cells, driving expansion of adaptive NKG2C+ NK cells and subsequent enhancement of ADCC responses." (PMID 32132995, 2020). "HLA-E is broadly expressed at low levels, and its expression can be up-regulated during cellular stress, such as viral infection." (PMID 31394776, 2019). "Little is known about the relevance of HLA-E concerning viral infection and reactivation after solid organ transplant." (PMID 31394776, 2019). "Together, these results predict that exploitation of the universal HLA-E antigen presentation platform for immunotherapy of viral disease or cancer is feasible and will recruit an alternative T cell subset, which is quite conventional in its behavior." (PMID 29422902, 2018). "In stress conditions (viral infections, tumors), HLA-E can present peptides from other sources than the signal sequences of classical HLA-I molecules." (PMID 29709038, 2018). "Control of HLA-E cell surface expression by bacterial or viral infections and particularly human CMV is well established." (PMID 27493971, 2016). "HLA-E seems to play a major role in the immune response to different viral infections and to affect transplantation outcome, in Hematopoietic Stem Cell Transplantation, for example." (PMID 27493971, 2016). "HLA-G and HLA-E can co-operate to establish an immunosuppressive microenvironment in human tumors and viral infections, facilitating the escape of transformed cells from the recognition by the immune system." (PMID 25202308, 2014).
viral infections (continued). "We demonstrate that EBV and IFN-α, a cytokine that is induced by EBV and other viral infections, are also able to upregulate HLA-E." (PMID 23049954, 2012). "Interactions between the HLA‐E VL9 complex and NKG2A receptor exert an inhibitory effect on NK cells, and thus, when VL9 peptide supply is limited, such as in viral infection, where HLA class I is downregulated, this loss of signal releases NK cells from inhibition." (PMID 41543284, 2026). "The negative effect of the HLA-E*01:01 allele on viral infection was also observed in our previous analyses, where this genetic variant was correlated with an increased risk of CMV reactivation after allogeneic HSCT." (PMID 41153412, 2025). "Whether the HLA-E/virus-derived peptide complex could be recognized by CD94/NKG2A might be the key factor to determine the function of NK cells in virus infection." (PMID 40680069, 2025). "Therefore, the interaction between NKG2A/CD94 and HLA-E/peptide complex is closely correlated with the effects of NK cells in protection against viral infections or mediating immune escape." (PMID 40680069, 2025). "NKG2C may enhance NK cell activation through the interaction with HLA-E in complex with a peptide originated from the leader sequence of HLA-G, the increased expression of which often accompanies viral infections." (PMID 41573579, 2025). "In cases of viral infection or malignancies, the expression of HLA class I molecules may alter, which consequently will be reflected in the expression of HLA-E." (PMID 38601161, 2024). "Moreover, several malignancies and viral diseases express high levels of HLA-E, including hematological diseases." (PMID 33115963, 2020). "HLA-E surface levels serve as an important sensor of HLA class I expression and are sensitive to perturbations in the biosynthesis of most polymorphic class I allotypes as well as the class Ib molecule HLA-G imparted by viral infections or stress." (PMID 32132995, 2020). "Studies of viral diseases have shown that the various HLA-E genotypes affect a clinical outcome." (PMID 31394776, 2019). "HLA-E and HLA-G are immunoregulatory molecules and their cooperation has been found in immunosuppressive environments, including physiological (immune tolerance at maternal/fetal interface during pregnancy) and pathological (immune evasion of both tumor and viral infection) conditions." (PMID 37529053, 2023). "Moreover, Qa1 protein, a mouse homolog of human HLA-E protein, binds signal peptides derived from self class I molecules as NK sensors for viral infection as well as GroEL peptides from Salmonella typhimurium or mycobacterial peptides to stimulate a cytotoxic T-lymphocyte response against infection." (PMID 28066410, 2016). "HLA-G and HLA-E interaction may also take place during viral infections." (PMID 25202308, 2014). "Nevertheless, IFN-α may be a relevant inducer of HLA-E expression during virus infection." (PMID 23049954, 2012). "Across multiple viral infections (CMV, SARS-CoV-2, HBV, and HIV), HLA-E acts as a central immune modulator, balancing NK cell inhibition and CD8+ T-cell activation." (PMID 41440003, 2025). "The HLA-E peptide complex is recognized by the CD94/NKG2A heterodimer receptor expressed on activated NK cells and on a subset of CD8+ T cells during viral infections and in tumors." (PMID 39706891, 2025). "Regarding adaptive immunity, HLA-E presents pathogen-derived peptides and elicits specific CD8+ T cell responses, whereas HLA-G expression during viral infections correlates with immunosuppression and viral persistence." (PMID 41440003, 2025). "The overexpression of HLA-E is also observed in viral-infected cells, and the NKG2A-HLA-E axis is proved to exert a vital role in viral infection." (PMID 36032104, 2022). "The upregulation of HLA-E, the ligand of NKG2C, is a common feature found in viral infections, such as dengue, hantavirus, and HIV." (PMID 33042136, 2020).
viral infections (continued). "Of note, in the absence of any viral infection, TCD32dim cells showed intrinsically higher HLA-E expression." (PMID 35616530, 2022). "Since the HLA-E*01:03 variant consistently shows higher cell surface expression compared to HLA-E*01:01, the baseline engagement of the inhibitory CD94/NKG2A might even be higher during viral infection, thus promoting viral immune escape." (PMID 31394776, 2019). "However, transfection of lung epithelial cells with the S1 protein results in reduced degranulation and secretion of IFN by NK cells, accompanied by increased expression of HLA-E and NKG2A, which can lead to NK cell exhaustion as observed in other viral infections." (PMID 40497938, 2025). "Finally, recent studies have investigated the role of nonclassical HLA class I HLA-E in the control of viral diseases." (PMID 33807915, 2021). "While HLA-E-restricted regulatory CD8+ Tcellresponses have been described in human autoimmune disease, such as type 1 diabetes, such regulatory phenotypes are not well characterized in the context of viral infections." (PMID 41283666, 2025). "Often in conditions of viral infections or in a number of malignancies, expression of classical MHC class I proteins is abrogated by inhibition of TAP transporter and there are no HLA-derived peptides to present in complex with HLA-E." (PMID 31690066, 2019).